CD44 (CD44 molecule (IN blood group))
Diseases named in the same sentence as CD44 in open-access papers (continued):
Sharing a sentence is not in itself a finding about the gene and the disease.
cancer (continued). "Notably, CD44 and ALDH1A115 - established cancer stem cell markers displayed strong positive correlations with pseudotime, reinforcing the established role of a stem-like phenotype in metastatic progression." (PMID 40523956, 2025). "Interaction analyses of the cancer stem cell phenotypes, T cells and stromal cells revealed that phenotypes with similar marker expression tended to more closely interact, such as ALDH1/CD44 with ALDH1/CD44/SOX9, ALDH1 with ALDH1/SOX9 and CD44 with CD44/SOX9." (PMID 39888143, 2025). "Additionally, CD44 can bind nuclear STAT3 and p300 acetyltransferase, promoting STAT3 acetylation, which enhances cell proliferation and cancer stem cell like properties in colon and other cancer cells." (PMID 40438109, 2025). "Our results collectively suggest that the important parameter for HA in cancer progression is its molecular flexibility for binding to CD44, rather than HA molecular weight." (PMID 40881990, 2025). "While there was a decrease in the CD44+ cancer stem cell marker, there was no change in CD133 expression like the MCF-7 cell line." (PMID 41154846, 2025). "As CD44 is also a negative prognostic factor in various cancers, this effect reinforces the therapeutic potential of selected WCCPSs." (PMID 40284312, 2025). "Besides, by evaluating the expression levels of cancer stem cell (CSC) surface markers, EpCAM, CD24, CD133 and CD44 by flow cytometry, we confirmed a direct correlation between stemness markers levels and PHGDH expression in HCT8 and RKO P1 colonspheres." (PMID 40640948, 2025). "Many other peptides have been chosen not as ligands in assays but rather to modulate CD44 activity and study its effect on cancer development." (PMID 41440277, 2025). "Furthermore, we also observed the downregulation of the mRNA expression of several key cancer stemness markers following CLF treatment, including CD44, CD24, BMI1, and HES1." (PMID 41303378, 2025). "We found cancer cell migration in both dilute HMW-HA and LMW-HA, but cell migration was inhibited in higher concentration HMW-HA gels which 1H NMR measurements showed did not have sufficient molecular flexibility to achieve strong binding to the CD44 HABD." (PMID 40881990, 2025). "ARID1B OE significantly increased the number of spheroids and elevated the portion of CD44+/CD24‐ and ALDH‐positive cancer stem cell populations, suggesting that ARID1B plays a critical role in promoting cell survival and the maintenance of cancer stem cells." (PMID 40671262, 2025). "The results indicate that USP7 might influence cancer cell stemness by potentially altering the expression of stemness markers like CD44, CD133, and Nanog, known for their link to the stem‐like traits of cancer cells." (PMID 40078091, 2025). "Since the shift in CD44 isoforms is essential for EMT and ESRP1 is a master SF in EMT, it is plausible that CD44s and the depletion of ESRP1 represent a common pathway in the EMT process in cancer." (PMID 40538061, 2025). "Furthermore, our study demonstrates that circ_0000467 promotes cancer stem cell (CSC) characteristics, as evidenced by increased spheroid formation and elevated levels of CSC markers (CD24, CD44, EpCAM, SOX2, and Nanog)." (PMID 40290725, 2025). "CD44 and CD109 are both cell surface glycoproteins that play significant roles in cancer biology." (PMID 40227788, 2025). "Additionally, it targets oncogenic mRNAs, including CD44 and CDK1, and leads to reduced proliferation and migration in various cancers." (PMID 41388527, 2025). "CD44, CD133, Epithelial cell adhesion molecule (EpCAM/CD326), stage-specific embryonic antigen-4 (SSEA-4), CD146 are expressed on the surface of EVs originating from cancer stem cells and bind their specific antibodies immobilized on the beads." (PMID 40106404, 2025).
cancer (continued). "P. gingivalis increases oral cancer cell invasiveness by inducing EMT-like changes and expression of the cancer stem cell (CSC) markers CD44 and CD133, while the production of MMP degrades extracellular matrix and basal components, which also promotes cancer invasive metastasis." (PMID 40843171, 2025). "A study identified VCAN as a key upregulated gene in CAFs that promotes the motility and invasion of OC cells by activating the nuclear factor-κB signaling pathway and upregulating CD44, MMP-9, and hyaluronan-mediated motility receptor expression in cancer cells." (PMID 40369674, 2025). "Furthermore, CD44 isoform switching induced by EMT can modify the binding affinity and downstream signaling of HA, further shaping cancer cell behavior." (PMID 40178908, 2025). "Cell surface markers, such as CD147, CD44, and CD133, can serve as reliable prognostic biomarkers to predict the progression of oral precancer and cancer and may be valuable drug targets." (PMID 41305000, 2025). "CD44 is a nonkinase transmembrane receptor upregulated in mesenchymal subpopulations of cancer cells and recognized as a molecular marker for CSCs." (PMID 40342488, 2025). "While there was a decrease in the CD44+ cancer stem cell marker, no change was detected in the other marker, CD133 expression." (PMID 41154846, 2025). "For example, CD44, ARIH2, CSDE1 (also known as UNR), CYB5B, SF3B1, and RCN2, which have been reported to be overexpressed in cancer, showed an increased proportion of shorter 3′-UTRs, primarily as a result of alternative cleavage and polyadenylation (APA)." (PMID 40702779, 2025). "This creates a feedback loop where SPP1 activates the SPP1/CD44 axis and downstream PI3K/AKT and MAPK pathways, promoting epithelial-mesenchymal transition (EMT), autophagy, aberrant glucose metabolism, and reduced drug uptake in cancer cells." (PMID 41391064, 2025). "Besides CD44, VCAN binds to TLRs, promoting the secretion of pro‐inflammatory cytokines (TNF‐α, IL‐6) that prevent cancer cell apoptosis and enhance metastasis." (PMID 40542654, 2025). "Unlike treatments that focus on single molecular markers, CD44-targeted nanocarriers use a complete targeting strategy that encompasses all aspects of cancer development, going beyond individual indicators." (PMID 41367861, 2025). "CD44 is a nonkinase glycoprotein and a receptor for hyaluronic acid that has upregulated expression in many types of cancer-initiating cells (CICs) or cancer stem cells (CSCs), as well as in rapidly proliferating cells." (PMID 39815326, 2025). "CD44 AS has been reported to be relevant to metastasis and EMT in many types of cancer." (PMID 40282339, 2025). "Moreover, CD44 on ADSCs interacts with MMPs, influencing ECM remodeling and aiding cancer cell infiltration." (PMID 40369674, 2025). "We found that a lack of MCPIP1 RNase activity induces the expression of cancer stem cell markers such as c-Myc and CD44." (PMID 39815326, 2025). "Both CD44 and CD133 are widely used surface markers for cancer stem-like cells." (PMID 40708945, 2025). "In cancer cells undergoing EMT, experimental inhibition of HA synthesis (e.g., 4-MU) or CD44 silencing (e.g., by RNAi) leads to the suppression of EGFR activity and downstream signaling pathways (ERK, AKT), resulting in the reversal of the EMT phenotype and attenuation of cell invasiveness." (PMID 41009438, 2025). "CD44 and CD133 are widely recognized markers for identifying cancer stem cells." (PMID 41154846, 2025). "Specifically, in the SCC-55 cell line, a subset of cells identified as side population (SP) cells—characterized by Hoechst 33342 dye efflux via ABC transporters—exhibited elevated expression of both CD44 and CD147, highlighting their enrichment in cancer stem cell-like traits." (PMID 41479915, 2025).
cancer (continued). "In squamous cell carcinoma (SCC), both myCAFs and iCAFs were involved in secretion of collagens and fibronectin 1, which can interact with CD44 on SCC keratinocytes and lead to increased cancer cell proliferation and invasion by activating PI3K/AKT and Src/MAPK signalling pathways." (PMID 39780187, 2025). "Notably, the expression of the standard isoform of CD44 was upregulated by ZEB1, and ERK activation was elevated in mesenchymal-like cancer cells." (PMID 40178908, 2025). "Also, metformin has been shown to downregulate the expression of stem cell markers such as CD44 and ALDH in cancer cells, potentially impacting LSC properties." (PMID 38790277, 2024). "Notably, CD10+GPR77+ and CD44+ CAFs, when co-cultured with cancer stem cells and PDAC cancer cells, exhibit increased tumorigenesis, chemoresistance, and disease recurrence." (PMID 38361931, 2024). "Stemness-related genes have been found, such as SOX2 (sex-determining region Y-box 2), NANOG (Nanog homeobox), and OCT4 (octamer-binding protein 4), along with the expression of the surface markers CD133+ and CD44+ and chemokine markers such as CXCR4 on cancer stem cells as stemness markers." (PMID 39684461, 2024). "There are many markers that could differentiate CSCs from NSCs such as CD44, CD133, CD24, EpCam, ALDH1A1, etc.; these markers are highly expressed in wide types of cancer 25-27." (PMID 39513121, 2024). "The upregulation of CD44 and the downregulation of ITGA6 in TPCS also suggested a stem‐like phenotype, which may contribute to its ability to generate diverse cancer cell progeny." (PMID 38582099, 2024). "Interestingly, the hyaluronan–CD44 axis induces the epithelial-to-mesenchymal transition—EMT—process and affects cancer cell stemness, probably through Akt pathway signaling." (PMID 38398174, 2024). "Thus, we also examined expression levels of HNSCC specific cancer stem cell (CSC) markers, CD44 and ALDH, as well as other markers for HNSCC stemness, SOX2, NANOG, and BMI1." (PMID 38435825, 2024). "Finally, we performed KEGG enrichment analysis of SPP1 signaling pathway receptors (CD44, ITGB1, ITGB6) that were expressed in epithelial cells in 33 cancers, and extracted the intersections of the enriched pathways." (PMID 38648200, 2024). "As a non-kinase cell surface transmembrane glycoprotein, CD44 is highly expressed in various human cancer cells." (PMID 38649957, 2024). "YBX1 has predictive value for drug resistance and poor prognosis in more than 20 cancer types, and upregulates the expression of multiple drug resistance genes, including ABCB1, MVP/LRP, TOP2A, CD44, CD49f, BCL2, and MYC, upon UV irradiation or Cisplatin treatment." (PMID 39168971, 2024). "The CSCs biomarkers, such as CD44 and CD133 were checked by FACS and immunoblotting, and the in vivo and in vitro CSCs properties assays proved that this protocol sorted side population is cancer stem-like cells." (PMID 38462600, 2024). "In combination with existing reports and GBP1-regulated AS events, a regulatory pathway was finally obtained, that is, GBP1 regulated CD44 protein expression through A3SS alternative splicing after binding to HNRNPK, and finally played a role in promoting cancer." (PMID 38167153, 2024). "CD44 is a non-kinase transmembrane glycoprotein and is overexpressed in several cell types, including cancer stem cells." (PMID 38798768, 2024). "CD44 acts as a linker between MT1-MMP and the actin cytoskeleton in inactive cancer cells." (PMID 38736891, 2024). "To clarify the specific signaling pathways regulated by CD44, we performed GSEA and confirmed that CD44 mainly participated in inflammatory responses, interferon, interleukin, EMT, and KRAS signaling pathways in pan-cancer." (PMID 38590654, 2024). "CD44 and RHAMM also exhibit compensatory effects; thus, targeting HA receptors for cancer therapy may be necessary to silence both receptors to completely abolish the corresponding HA signalling." (PMID 38791985, 2024).
cancer (continued). "Several phase I and II clinical trials have commenced using ASOs as cancer therapeutics; however, the use of CD44-specific ASOs has not yet been investigated." (PMID 38612911, 2024). "In various cancer models, HA amplifies cell proliferation and migration by engaging with RHAMM and activating additional receptors that govern the PI3K/AKT and ERK pathways, including CD44, PDGFR, and EGFR." (PMID 38791985, 2024). "CD44 serves as a robust marker of CSCs in CRC and is functionally essential for cancer initiation." (PMID 38167453, 2024). "In this regard, CD44 represents an HA receptor therapeutically interesting since it is known to be upregulated in cancer-initiating or metastasizing cells, and involved in the epithelial-mesenchymal transition (EMT), cancer cell survival and drug resistance." (PMID 38600583, 2024). "Although molecular targeting of the Wnt signaling system has been proposed and trialed for the treatment of various cancer types without significant success yet58,59, Wnt signaling, particular CD44, should be potential target in the future." (PMID 39496635, 2024). "Additionally, to evaluate the effect of HNF4A on the stemness of the spheroids, we screened for expression of cancer stem cell markers, including CD24, CD44, NESTIN, OCT4, and SOX2." (PMID 39165427, 2024). "Cancer stem cell (CSC) markers, such as CD44, CD29, and CD90, could also induce EMT-related radioresistance through various pathways." (PMID 38662050, 2024). "In the present experiments, Abs to block GPNMB or CD44 were effective for at least 35 days despite an expected half-life of 6–8 days in mice, reflecting the advantage of targeting a renewable ESC population as done for cancer therapies." (PMID 39052353, 2024). "Successful preclinical NIR-PIT studies against cancer and cancer-stem like cell antigens have been performed against more than 20 different molecular targets expressed on different cancers including EGFR, HER2, PSMA, CD25, GPC3, mesothelin, CD133, CD44, CEA, DLL3, PD-L1, and others." (PMID 38658501, 2024). "Similarly, in the same cancer, CD44 was targeted through the direct administration of ON-TARGET plus human CD44 siRNA or indirectly by silencing mucin (MUC5AC) gene expression using a small hairpin RNA construct (pSUPER-Retro-shMUC5AC)." (PMID 38672650, 2024). "In colon cancer, several studies have reported on the identification of cancer stem cells (CSC) earmarked by specific membrane-bound antigens such as CD133, CD44, and CD166, used to enrich for cells with tumor-propagating capacity in limiting dilution transplantation assays." (PMID 39246444, 2024). "The interaction between CD44 and PKM2 enhances the glycolytic phenotype of cancer cells." (PMID 37953485, 2024). "CD44 is recognised as a characteristic surface marker for CSCs, often used alone or alongside other markers like CD24, CD133, CD34, and c-Met, to isolate or concentrate CSCs in different cancer forms." (PMID 38920995, 2024). "Correlation analysis between RFC4 and checkpoint gene expression in different types of cancers showed a high correlation with immune genes including CCL4, CCL16, HLA family genes, TNFRSF8, TNFRSF14, TNFRSF18, CD70, CD44 (p < 0.05), CD276, CX3CL1 and VGEGFA (p < 0.05)." (PMID 39031628, 2024). "As reprogramming to cancer stem cells’ state could potentially be indicative of the effect of senescent ASCs, we measured the levels of CD24, and CD44 after conditioning MCF10A1 cells with medium from ASCs and ASCs that were senesced." (PMID 38473331, 2024). "In general, however, CD44 was positively related to infiltration of macrophages, neutrophils, and CD4+ memory T cells, but negatively related to T follicular helper cells, B cells, NK cells, and regulatory T cells (Tregs) in most cancers." (PMID 38590654, 2024). "Furthermore, the interaction of CD44 with IQGAP1, an actin-binding protein that regulates cell–cell and cell–matrix adhesion, was also observed in standard and cancer cells." (PMID 38672650, 2024).
cancer (continued). "Consistent with the effects of CAF-derived exosomes, circ_0067557 overexpression reduced apoptosis and promoted cancer stem cell (CSC) features (CD133, CD44, and OCT4 protein expression) in HCT116 cells, while circ_0067557 knockdown caused the opposite effects." (PMID 38216964, 2024). "In addition, employing western blot and RT-qPCR analysis, our investigation demonstrated a substantial decline in the levels of cancer stem cell markers CD133 and CD44 within the knockdown groups." (PMID 38413558, 2024). "The analysis of the tumoral markers p27, CD44, Fibulin-3, and NANOG and the expression of genes related to cancer transformation such as NANOG, CDH-1, and Zeb-1 showed that the simulated microgravity environment led to expression patterns in MeT-5A cells similar to those observed in BR95 cells." (PMID 39451527, 2024). "Furthermore, cancer cells with increased BNIP3/BNIP3L transcriptional activity exhibited CSC features, such as greater mammosphere-forming ability and high CD44 levels." (PMID 38834039, 2024). "Likewise, 92% of the Hs-578t cancer cells showed the CD44+/CD24− immunophenotype, whereas the CD24−/CD44−, CD24+/CD44+, and CD44−/CD24+ subpopulations constituted 7.7%, 0.2%, and 0%, respectively." (PMID 38392969, 2024). "CD44 functions as a glycoreceptor for HA and further ECM components, is involved in matrix degradation, carries glycoligands for E‐, P‐ and L‐selectins, and determines EMT and CSC states in several cancers." (PMID 37849446, 2024). "Multiple investigations have revealed distinct CD44 expression patterns between cancer stem cells and their non-cancer stem cell counterparts across various solid tumors." (PMID 38170015, 2023). "CD133, CD44, and ALDH are critical surface markers in cancer stem cells." (PMID 36824410, 2023). "Since CSCs are implicated in the growth, migration, invasion, angiogenesis, anti-cancer drug resistance, and metastasis in MIBC, the influence of Chaga on the expression levels of three important CSC markers, CD44, SOX2, and YAP1 which were upregulated in most of MIBC were examined." (PMID 37153767, 2023). "The authors analyzed the expression levels of CD44 in a clinical dataset and found that BSH-polyR might be suitable for certain types of malignant tumors." (PMID 37627119, 2023). "The increased expression of CD133, CD9, and CD44, along with SOX9, TUBB3, MGMT, and ABCG2, may have led the GBMs on a path of acquiring cancer-specific stemness." (PMID 36834653, 2023). "In the cancer patient samples, we would expect a similar high percentage of CD44+ CRC elevation when compared to the noncancer afflicted cohort yet, a marker increase in CD44i35 marker." (PMID 36100762, 2023). "Cluster of differentiation-44 (CD44) is a member of the non-kinase, single-span transmembrane glycoproteins family, which can contribute to cancer stem cells (CSCs) function and is generally recognized as a molecular marker for CSCs9." (PMID 37117249, 2023). "But, in other cancers, an increased level of CD44 expression did not correlate with patient outcomes." (PMID 37005380, 2023). "In addition, we found that cancer stemness markers, such as SOX2, Nanog, CD44, CD133, and ALDH1 were significantly upregulated in xenograft tumors overexpressing SAMD9." (PMID 36757050, 2023). "We then explored by real-time qPCR the impact of miR-662 overexpression in MDA-MB-231 cells on expression levels of well-established stemness markers that are involved in embryogenesis and cancer –NOTCH1, WNT7b, ZEB1, TCF3, CTNNB1, CD44, CD24, SNAI2, OCT-04, c-MYC, EZH2–." (PMID 37443350, 2023). "Cancer stem cells markers represented by CD133 expression were present in a broad range from 0.0% to 46.0% with a median value of 0.5%; CD44 from 20.0% to 100.0% (median value 91.0%); and cells with CD24 expression were present from 0.0% to 16.0% (median value 7.0%)." (PMID 37958844, 2023).